CCL5 (C-C motif chemokine ligand 5)
Diseases named in the same sentence as CCL5 in open-access papers (continued):
Sharing a sentence is not in itself a finding about the gene and the disease.
infection (continued). "As for H5N1/2004 infection, CCL-5/RANTES and CXCL-10/IP-10 were found to be induced to >1000 folds; whereas TNF-α and IL-8 were expressed at 200-300 folds." (PMID 21108843, 2010). "Although no significant cytokine/chemokine induction was observed during the early phase of H1N1 infection; IP-10/CXCL-10, TNF-α, TGF-β2, CCL-5/RANTES, IL-8, and IL-6 were found to be 4-450 folds induced during the late phase of infection." (PMID 21108843, 2010). "At 6 hours post-H5N1/2004 infection, there were marked increase in the expression of CXCL-10/IP-10 and CCL-5/RANTES (60-120 folds); while there were only relatively minor increase in IL-6 and IL-8 expression (2-10 folds)." (PMID 21108843, 2010). "To this effect, we observed that although MyD88 mice present with reduced immune cell activation following CB4 infection, they produce similar levels of TNF-α and CCL5 compared to WT mice." (PMID 19122812, 2009). "Following infection significant increases of CCL2 (MCP-1), CCL3 (MIP-1α), CCL4 (MIP1-β), CCL5 (RANTES) and CXCL9 (MIG) were observed in WT NOD mice compared to uninfected controls." (PMID 19122812, 2009). "One study has found that infection with SHIV can lead to decreased levels of CCL3, CCL4, and CCL5 in PBMCs during the acute phase of infection." (PMID 19149556, 2009). "Virally, stimulatedpDC produces chemokines, such as CCL3 (MIP-1a), CCL4 (MIP-1b), CCL5 (RANTES),CXCL8 (IL-8), and CXCL10 (IP-10) which stimulate Th1, and NK cells homing tosite of infection through IP-10 and CCL4, respectively." (PMID 19190769, 2008). "Infection of WT mice with rMA15 resulted in a significant induction of proinflammatory chemokines including CCL2 (MCP-1), CCL3 (MIP-1α), and CCL5 (RANTES) as compared to mock-infected control mice." (PMID 19079579, 2008). "A significant increase in CCR5, CCL5, and IFNγ gene expression in the spleen and ILN was observed 7 days after genital infection when compared with levels before infection." (PMID 18700040, 2008). "By PID 180, expression of CC-chemokines returned to pre-infection levels (CCL4 and CCL5), or even increased (CCL3)." (PMID 17684570, 2007). "At the chronic stage of SHIVSF164P4 infection, expression of the CCR5 ligands returned to pre-infection levels (CCL4 and CCL5), or even increased (CCL3) in all three GALTs." (PMID 17684570, 2007). "gondii infection, but not parasite lysates, robustly induces transcriptional and secretory upregulation of the chemokine C-C motif ligand 5 (CCL5/RANTES) in primary brain endothelial cells and dendritic cells (DCs)." (PMID 41528135, 2026). "In the case of MHV-JHM infection, changes in expression (from 0% to 100%) were visible in IL-6, IL-18, IL-33, ENA-78 (CXCL5), GRO alpha (CXCL1), IP-10 (CXCL10), MCP-1 (CCL2), MIP-1 beta (CCL4), MIP-2 alpha (CXCL2), RANTES (CCL5), and TNF alpha." (PMID 40358160, 2025). "In the striatum, we also see clustering within the fentanyl-treated groups based on infection status: EcoHIV-infected mice treated with fentanyl had higher concentrations of CCL2, CCL4, CCL5, and CCL11 but lower levels of CCL3 and CXCL10 than the uninfected, fentanyl-treated animals." (PMID 40447886, 2025). "CCL5 and CXCL11 recruit T cells and other immune cells to sites of infection." (PMID 41258789, 2025). "The concentration of chemokines CxCL1/KC/GRO-α, CxCL2/MIP-2, CCL5/RANTES and cytokines TNF-α, IL-1β, IFN-γ, IL-5, IL-6, IL-9, IL-10, IL-13, IL-17, IL-23 circulating in blood were measured in experimental animals on day 15 post-infection." (PMID 40445994, 2025). "In particular, CCL5 is significantly upregulated from the early stages of infection in those with mild disease, but not in severe cases." (PMID 41155463, 2025). "Moreover, STAT1-dependent chemokines including CCL5, CCL8, CXCL10, and CXCL11 showed a slight increase during the early stage of infection, the most significant increase occurred after 10 h.p.i, peaking at 24 h.p.i." (PMID 40934228, 2025).
infection (continued). "On the one hand, they observed that the chemokine (C-C motif) ligand 5 (CCL5) was elevated in SIDS cases with mild upper airway infections when compared to those without evidence of infection." (PMID 38617004, 2024). "In summary, infection with the H7N7 IAV subtype stimulated the secretion of pro-inflammatory cytokines and chemokines in a microglia-dependent manner, with a higher secretion of CCL2 and CCL5 as well as IFN-β in female-derived cultures." (PMID 39171200, 2024). "CCL5 mRNA was increased at 24 h and peaked at 48 h after RV16 infection (p < 0.001)." (PMID 39598462, 2024). "For example, during early infection of P. falciparum, the infected RBC-derived PFHRPII interacted with BMECs, activating endothelial NFκB signaling, leading to the release of inflammatory mediators such as IL-6 IL-1B CCL5 and IFNβ1." (PMID 38360663, 2024). "In our review, we found most frequently increased CCL2 (41.7% in vitro, 45.5% in vivo, and 33.3% in human serum during the acute phase of infection), CCL5 (50% in vitro, 38.6% in vivo), and CXCL10 (41.7% in vitro, 40.9% in vivo, and 33.3% in human serum during the acute phase of infection)." (PMID 38543749, 2024). "The amount of CCL5 (RANTES) secreted (CCL5.secretion) is negatively correlated with total bacteria, which reinforces the impact of CCL5 driven recruitment of T cells to the site of infection." (PMID 40809472, 2023). "Infection with virulent ASFV isolates often results in exacerbated immune responses, with increased levels of serum pro-inflammatory interleukins (IL-1α, IL-1β, IL-6), TNF and chemokines (CCL2, CCL5, CXCL10)." (PMID 36680273, 2023). "Levels of proinflammatory chemokines and cytokines CXCL1, CCL5, IFN-γ, IL-1β, CXCL10, IL-17, TNF-α and IL-6 were also assessed in the brain, spleen and liver of MAYV-infected mice throughout the infection." (PMID 36902230, 2023). "Additionally, CCL signaling pathways were involved in cell interaction between CD8+ Trm cells and other cells, with Ccl4-Ccr5 and Ccl5-Ccr5 ligand/receptor pairs being important between CD8+ Trm and other memory subsets after infection and reinfection." (PMID 37415817, 2023). "Data on gene-fold change for IFNB1, CCL5, CXCL11, CXCL10, and IDO1 after experimental infection of HLMVEC by pathogenic (ANDV, HTNV) and nonpathogenic (PHV) viruses were recorded at seven timepoints t = 0, 12, 24, 36, 48, 60, 72 hpi." (PMID 37766212, 2023). "However, at 30 days post-infection, TNF-α, IL-6, KC, CCL3, CCL2, CCL20, CXCL11, CCL11), CCL27, CXCL5, CXCL12 and CCL5 were all significantly higher in the BAL fluid of Duox1 KO compared to WT mice." (PMID 36936954, 2023). "It is, therefore, conceivable that CCL-4, CCL-5, CXCL-10 and IL-8 would initiate and maintain the inflammatory response in the acute phase of infection and the increased release of CCL-2 during the convalescent phase would regulate the immune response in order to reduce immune pathologies." (PMID 35543881, 2022). "Among the tested chemokines, only CCL5 protein levels were upregulated in response to ONNV (from MOI 10−3 to 1) infection at 24 h with a fold increase of 4 (223 pg/mL ± 50.8, p < 0.01) after ONNV MOI 1 infection." (PMID 36611893, 2022). "MC-derived CCL-5 appears to be critically involved in attracting antiviral CD8 T cells to sites of infection, specifically to the lungs, but it is not contained in the granules and is thus not released upon MC degranulation." (PMID 35563708, 2022). "The CCL5 mRNA levels increased in the medium-dose group by 7 weeks post-infection, but there was no change in the low-dose group." (PMID 36051240, 2022). "Finally, a high number of pro-inflammatory cytokines were up-regulated upon infection, such as CXCL10, CCL5, CXCL11, TNF, CCL3, CXCL8, and IL6." (PMID 35893684, 2022). "RANTES, or CCL5, is a chemokine from the CC subfamily that is a strong inflammatory mediator with chemotactic properties for immune cells in the place of injury or infection." (PMID 35330038, 2022).
infection (continued). "In this setting, TAT-I24 significantly reduced the transcript levels of Ccl7, Cxcl10 and Ccl5 2 h post-infection, indicating that the inhibitory effect of the peptide is not linked to the reduction of viral gene expression." (PMID 35806257, 2022). "In the case of infection, serum neutralizing antibody titer against the WT strain exhibited a significant positive correlation with CCL5 (coefficient: 0.73, p = 0.02) and a negative correlation with G-CSF levels (coefficient: −0.69, p = 0.03)." (PMID 36366324, 2022). "Chemokine ligand 5 (CCL5; also known as RANTES), an important chemokine found in eosinophil granules, is required for normal T-cell function and for recruiting other lymphocytes, such as monocytes and T-cells, to the site of infection/inflammation." (PMID 35140270, 2022). "The immunocompetent mouse model of intravenous infection with mCMV indeed revealed that the wave of MC-dependent CCL-5 is followed by lung infiltration with antiviral CD8 T cells that confine and eventually resolve tissue infection within nodular inflammatory foci (NIF)." (PMID 35563708, 2022). "Similarly, while SARS-CoV-2 infection alone induced a minimal expression of the inflammatory chemokines, the IAV single-infection group induced significantly high levels of CCL3, CCL4, CCL5, and CXCL9." (PMID 35107382, 2022). "Moreover, CSE significantly downregulated c-c motif chemokine 5 (CCL5) and Toll-like receptor 3 (TLR3) while these genes were upregulated upon Sp only infection (cluster 1 and 5)." (PMID 35681466, 2022). "As the MC-derived CCL-5 has its serum peak on day two, and as MC-enhanced control of lung infection was still operative in TLR3 knock-out mice, our interest turned to MC degranulation triggered by the infection of MC." (PMID 35563708, 2022). "In addition, the levels of filaggrin, VEGF, MIP-1β, RANTES/CCL5, HIF-1α and IL-1β were identified as infection biomarker molecules with AUC values > 0.72, having the next values of specificity (> 79%) and sensitivity (> 55%)." (PMID 36482106, 2022). "The expression of CCL5/RANTES decreased in all infections in the presence or absence of implants compared to sterile implants." (PMID 35203495, 2022). "For example, heat-iMVA infection triggered higher levels of IFN-inducible genes than MVA, including Ifih1 (MDA5), Ddx58 (RIG-1), Oasl2, Oas3, TLR3, Nod1, Ifna4, Ifnb1, Ccl5, Cxcl9, Cxcl10, and members of the guanylate binding protein (Gbp) family, as largely dependent on STING (marked as b)." (PMID 36261460, 2022). "Increased expression of CCL5 and CXCL10 could enhance recruitment and activation of immune cells and resident neuronal cells at the site of infection, thereby promoting the clearance of free virus as well as of infected cells in the CNS." (PMID 33407600, 2021). "However, despite the weak replication level at high MOI, we were able to detect some cytokine response following infection as observed by the expression of IL-6, IFN-β and CCL5 in brain endothelial cells." (PMID 34386007, 2021). "There was prominent induction of IL-6, CCL3, and CCL4 in genotype 1 infected decidua and placenta compared to genotype 3 while expression of TNF-α, IL-15, IL-18, and CCL-5 was barely detected regardless of infection." (PMID 34502167, 2021). "Furthermore, it was determined that CCL5 was upregulated in vaginal tissue following immunisation and that CCL5 was required to retain CD4+ TRMs at the site of infection." (PMID 33668777, 2021). "At 24 h post-infection, serum levels of IL-6, IL-17A, TNF-α, and IFN-γ were greatly reduced in IL-38-treated group, CCL2 and CXCL10 decreased at day 4, IL-1β and CCL-5 decreased on day 7 in the IL-38-treated group compared with group without IL-38 treatment." (PMID 33414457, 2021). "Furthermore, within the first 48 h of infection, the production of CXCL5, CCL3, CCL5, and, to a lesser extent, GM-CSF, was reduced." (PMID 33670363, 2021).
infection (continued). "Several chemokines potentially attract neutrophils during an infection and S. suis infection induces the production of many of them, such as CXCL1 (KC), CXCL2 (MIP-2), CCL2 (MCP-1), CCL3 (MIP-1α), CCL4 (MIP-1β) and CCL5 (RANTES)." (PMID 34835517, 2021). "In addition, the 040417 strain reduced the production of CXCL8 at the two times points evaluated and diminished the levels of CCL5 and CXCL10 at hour 72 post-infection." (PMID 34064210, 2021). "The infection of murine in vitro generated Hoxb8 neutrophils with A. phagocytophilum induced the expression of inducible or type 2 nitric oxide synthase (iNOS or NOS2) mRNA and the secretion of significant amounts of MIP-1α (CCL3), RANTES (CCL5), and TNF." (PMID 33747981, 2021). "Following infection of the CNS, microglia express markers characteristic of M1 activation including increased expression of Iba-1, as well as chemokines such as C-C motif cytokine 2 (CCL2), CCL3, CCL5, and CCL7." (PMID 32872152, 2020). "Further, in vitro infection of human type II alveolar epithelial cells maintained at an air-liquid interface led to productive virus replication and significant upregulation of CXCL10 and CXCL11, as well as CXCL8 and the Th1 cell-directed chemokine CCL5." (PMID 33613280, 2020). "CCL5, a CCR1 ligand, is a molecule secreted by activated T cells which leads to T cell chemotaxis and, therefore, the migration of immune cells at the site of infection." (PMID 32872518, 2020). "RANTES/CCL5 secretion levels by trophoblasts from non-affected twins increased 2.4- and 4.6-fold at 48 h or 96 h after infection with ZIKVBR, respectively, while IP10 secretion levels increased 16- and 96-fold." (PMID 32745093, 2020). "In this study, we found that the chemoattractive molecules CXCL10, CCL5, and CCL2 were potently released by the apical compartment upon ZIKV hBLEC infection, suggesting that circulating leukocytes could be attracted to the infected BBB." (PMID 32753493, 2020). "Infected MC degranulate and synthesize the CC-chemokine ligand-5 (CCL-5), which is released to attract protective virus-specific CD8 T cells to infected host tissue for confining and eventually resolving the productive, cytopathogenic infection." (PMID 32984069, 2020). "However, following infection, obese mice had increased circulating levels of B cell activating factor (BAFF, p = 0.0070), CCL5 (p = 0.0118), CCL17 (p = 0.0118), Chitinase-3-like 1 (p = 0.0118), CXCL5 (p = 0.0118), and IFN-alpha (p = 0.0118)." (PMID 32854687, 2020). "In addition, only trophoblasts from non-affected twins secreted significantly increased amounts of chemokines RANTES/CCL5 and IP10 after infection with ZIKVBR." (PMID 32745093, 2020). "Infection of human cortical collecting duct epithelial cells with BKPyV resulted in downregulation of TNFα expression, but upregulation of the TNF receptors 1 and 2, TLR3, RIG-1, IL-6, IL-8/CXC8, CCL5/RANTES, CCL2/MCP-1, and CXCL10/IP-10." (PMID 31408949, 2019). "Melatonin treatment (30 nM) reduced the levels of IL-6 (2-fold), MCP-1/CCL2 (5-fold), and RANTES/CCL5 (6-fold) compared to vehicle treatment after both 4 and 24 h of infection, while both vehicle and melatonin treatment reduced the levels of IL-10, MIP-2/CXCL2, and KC/CXCL1." (PMID 30949455, 2019). "Furthermore, these cells show a short-lived increase in secreted antimicrobials including elafin, CCL5 and secretory leukocyte peptidase inhibitor (SLPI) following infection." (PMID 31156637, 2019). "The infection of human macrophages induced the expression of pro-inflammatory cytokines/chemokines such as MCP-1/CCL-2, IFN-α2, IFN-γ, MIP-1α/CCL-3, IP-10/CXCL-10, RANTES/CCL-5, IL-8, TNF-α, IL-12p40, and IL-6." (PMID 30984127, 2019). "Additionally, in a study in vitro using a WT hRSV A2 strain (6340WT) and a recombinant strain that lacks the G-protein gene (6340ΔG), infection of NHBEs cells induced the secretion of CCL2, CCL5, and CXCL8 by both viruses." (PMID 30936869, 2019).
infection (continued). "On the 28th day of infection and 23 days of treatment, the euthanasia occurred, and the heart preserved for histopathological, oxidative stress (SOD, catalase, TBARs, carbonylated proteins) and plasma (CCL2, CCL5, TNF, IL-10) analyses." (PMID 30365644, 2018). "Severe IV infection induces many cytokines; IFNαβ, TNFα, IFNγ, C-X-C motif chemokine (CXCL) 10 (CXCL10), CXCL9, C-C motif ligand (CCL) 2 (CCL2), CCL4, CCL5 and interleukin (IL)−6 (IL-6), IL-2, IL-8, and IL-10 have all be observed to be upregulated during severe IV infection in humans." (PMID 30250466, 2018). "Expression of viral RNA, as well as Ccl5 and Cxcl10, but not Tnfα, Il6 Ccl2, Ifna and Ifnb, was significantly decreased in the footpads of Bclx+/- mice at 5 days post-infection." (PMID 30261081, 2018). "However, transcription levels of IFN-β, IFN-λ, ISG56, CCL5, and IL-6, and expression levels of STAT1, pSTAT1, and ISG15 were similar in A549 cells after infection with all 4 recombinant viruses." (PMID 30050872, 2018). "However, in the 4–99 epg infection group, there was a significant increase in CCL11 (p = 0.002) 3 months post-treatment, whereas, CCL5 and CXCL10 were significantly decreased (p = 0.009 and p = 0.002, respectively)." (PMID 30619332, 2018). "Chemokines, used to attract leukocytes to sites of infection, were also produced by ZIKV-infected Sertoli cells and RANTES (CCL5), fractalkine (CX3CL1), IP-10 (CXCL10) and GRO (growth related oncogene CXCL1) were found in the supernatant after 46 h of inoculation." (PMID 29751638, 2018). "CCR5 is widely expressed on T lymphocytes, macrophages, microglia, and dendritic cells and plays a critical role in inducing migration of immune cells to sites of infection and injury in response to elevated levels of certain C-C-chemokine ligands (MIP-1α/CCL3, MIP-1β/CCL4, CCL5/RANTES)." (PMID 30305110, 2018). "The elimination of MyD88 in cardiomyocytes determined a lower increase in CCL5, IFNγ and TNFα gene transcription during acute infection by T. cruzi parasites of the Y strain, but it did not significantly modify heart leukocyte infiltration and parasitism." (PMID 30067739, 2018). "By detecting extracellular T. cruzi through TLR2 and TLR4 at the moment of the infection, or intracellular T. cruzi through TLR9 and TLR7, the cardiomyocytes should activate the MyD88 pathway and induce CCL5 that will focus the recruitment of cytotoxic CD8+ T cells towards the infected cell." (PMID 30067739, 2018). "We first choose to measure the mRNA levels for iNOS, a gene that is transcribed in vivo by cardiomyocytes in response to LPS inoculation, as well as those for CCL5, CCL7 and CXCL10, three chemokines transcribed in newborn cardiomyocytes after in vitro infection with T. cruzi." (PMID 30067739, 2018). "In fact, TNF-α acts synergistically with IFN-γ to stimulate the production of nitric oxide (NO) by macrophages and influences the expression of chemokines, such as CCL5, CCL9, CXCL10, and CCL2, which induce migration to and maintenance of immune cells in the infection site." (PMID 28659665, 2017). "In each case, IL-6 and CCL5 induction was greater during infection with NH1125B than NH1067B (respectively) indicating that there are likely viral-specific factors involved in the degree of cytokine and chemokine induction during infection." (PMID 28877226, 2017). "HaCaT cells lacking IFI16 were also impaired in the secretion of CCL5 protein following infection with ultraviolet light-inactivated HSV-1." (PMID 28194029, 2017). "However, ECTV encodes vCCI decoy receptor, EVM1, which is an abundantly secreted glycoprotein during infection and can bind the CC chemokines to form highly stable complexes with CCL3 and CCL5." (PMID 29312229, 2017). "IL-8 and RANTES expressions were highest at this short-term time point, and IL-8 levels remained elevated compared to non-infected control cells also at 24 h after infection, while CCL5 mRNA expression levels dropped to background levels." (PMID 28912507, 2017).